NGDN (neuroguidin)
Description:
Part of the small subunit (SSU) processome, first precursor of the small eukaryotic ribosomal subunit. During the assembly of the SSU processome in the nucleolus, many ribosome biogenesis factors, an RNA chaperone and ribosomal proteins associate with the nascent pre-rRNA and work in concert to generate RNA folding, modifications, rearrangements and cleavage as well as targeted degradation of pre-ribosomal RNA by the RNA exosome. Its dissociation from the complex determines the transition from state pre-A1 to state pre-A1*. Inhibits mRNA translation in a cytoplasmic polyadenylation element (CPE)-dependent manner (By similarity).
Synonyms: CANu1; C14orf120; DKFZP564O092; LCP5; lpd-2; NGD
Tractability: Small molecule: a structure with a bound ligand is known. PROTAC: ubiquitination databases record sites on it; its protein half-life has been measured.
Gene: Protein-coding gene on chromosome 14 (23,469,679 to 23,509,862, forward strand). Ensembl gene ENSG00000129460.
Subcellular location: Nucleus; Nucleus, nucleolus; Chromosome, centromere; Cytoplasm; Cell projection, axon; Cell projection, dendrite; Cell projection, filopodium
Subcellular location (Human Protein Atlas): Mitochondria; Nucleoli; Nucleoplasm
Gene Ontology:
Molecular function: protein binding; RNA binding
Biological process: ribosomal small subunit biogenesis; maturation of SSU-rRNA; maturation of SSU-rRNA from tricistronic rRNA transcript (SSU-rRNA, 5.8S rRNA, LSU-rRNA)
Cellular component: nucleolus; small-subunit processome; cytoplasm; nucleus; axon; chromosome, centromeric region; dendrite; filopodium
Genetic constraint (gnomAD): Loss-of-function variants: 39 observed, 44.42 expected, observed/expected ratio (o/e) 0.88, 90% interval 0.68 to 1.15. The upper end of that interval is the gene's LOEUF score, 1.15, which puts it in group 5 of 6, group 1 being the genes least tolerant of losing a copy. Missense variants: 400 observed, 412.94 expected, observed/expected ratio (o/e) 0.97, 90% interval 0.89 to 1.05. Synonymous variants: 136 observed, 135.77 expected, observed/expected ratio (o/e) 1, 90% interval 0.87 to 1.15.
Homologues: Orthologues: chimpanzee NGDN (99% identical), macaque NGDN (97% identical), dog NGDN (92% identical), rabbit NGDN (91% identical), guinea pig NGDN (91% identical), rat Ngdn (90% identical), mouse Ngdn (89% identical), tropical clawed frog ngdn (60% identical), zebrafish ngdn (55% identical), Drosophila melanogaster CG11030 (43% identical), Caenorhabditis elegans lpd-2 (30% identical). Paralogues in human: UTP3 (21% identical).
Diseases named in the same sentence as NGDN in open-access papers:
NGDN is named in the same sentence as 14 diseases in open-access papers, as found by Europe PMC text mining. Sharing a sentence is not in itself a finding about the gene and the disease. The quoted sentences say what the papers report.
leukemia (3 papers, 2015 to 2021). A malignant (clonal) hematologic disorder, involving hematopoietic stem cells and characterized by the presence of primitive or atypical myeloid or lymphoid cells in the bone marrow and the blood. "NGDN encodes the E1F4E binding protein and, in leukemia cell lines, NGDN knockdown activates the mTOR pathway." (PMID 34400688, 2021). "AATF (also known as CHE1) participates in several cellular pathways, such as 40S ribosomal subunit synthesis in complex with NGDN (p = 0.0014, FC 0.95) and NOL10 (p = 0.0007, FC 0.85), and high AATF expression has been linked to variants of leukemia." (PMID 32192169, 2020). "The specific mechanism of action of NGDN in leukemia cells requires further study." (PMID 25887473, 2015).
myeloid leukemia (1 paper, 2015). A clonal proliferation of myeloid cells and their precursors in the bone marrow, peripheral blood, and spleen. "In this study, the effect of NGDN and its mechanism of action in human myeloid leukemia cells were investigated." (PMID 25887473, 2015). "The purpose of this study was to clarify the function of NGDN and its possible mechanism of action in human myeloid leukemia cells." (PMID 25887473, 2015). "The effects of NGDN over-expression were also confirmed in human myeloid leukemia line K562." (PMID 25887473, 2015).
pituitary adenomas (1 paper, 2021). "However, some variants were associated with the biochemical activities of GH-secreting pituitary adenoma, such as BCHE, DARS, NGDN, and UNC5B variants." (PMID 34400688, 2021). "Based on the ELISA and MTS assays, the variants in NGDN and BCHE may affect GH secretion and tumor growth in GH-secreting pituitary adenomas." (PMID 34400688, 2021). "The results from WES and targeted resequencing and clinical results from GH-secreting pituitary adenoma patients confirmed that variants in BCHE, DARS, NGDN, and UNC5B may be involved in GH secretion." (PMID 34400688, 2021).
pituitary tumor (1 paper, 2021). A benign or malignant neoplasm affecting the pituitary gland. "BCHE, DARS, NGDN, and UNC5B variants were associated with increased GH-secreting pituitary tumor biochemical activity, which was confirmed in vitro." (PMID 34400688, 2021). "Furthermore, GH-secreting pituitary tumors with variants in BCHE, DARS, NGDN, and UNC5B presented high biochemical activities including GH and IGF-1." (PMID 34400688, 2021).
cancer (4 papers, 2012 to 2024). A tumor composed of atypical neoplastic, often pleomorphic cells that invade other tissues. "Most of these genes have not been previously reported in SSs, and four genes, neuroguidin (NGDN), RAS protein activator like 3 (RASAL3), KLHL34 and MUM1L1, have not been previously linked to cancer." (PMID 26503545, 2015). "Most of these genes have not been previously reported in SS, and neuroguidin (NGDN), RAS protein activator like 3 (RASAL3), KLHL34 and MUM1L1 have not previously been linked to cancer; only one gene (EP300) has been reported in SS." (PMID 26503545, 2015).
tumor (3 papers, 2015 to 2022). "Furthermore, NGDN knock-down in K562/A02 cells resulted in the activation of multiple tumor-related signaling pathways, especially the mammalian target of rapamycin (mTOR) pathway." (PMID 25887473, 2015).
NGDN also shares sentences with these, for which no sentence is quoted: acute myeloid leukemia (1 paper); cervical carcinoma (1); endometrial cancer (1); Granuloma (1); infection (1); iron deficiency (1); migraine (1); Parkinson disease (1).